CCL2 (C-C motif chemokine ligand 2)
Diseases named in the same sentence as CCL2 in open-access papers (continued):
Sharing a sentence is not in itself a finding about the gene and the disease.
influenza (continued). "Importantly, IFN-β and CCL2 were also both overproduced at the protein level in influenza-infected Tpl2-/- mice, further supporting this mechanism of regulation." (PMID 34691044, 2021). "Additionally, we noted that increased IFN-β correlated with increased CCL2, CXCL1 and nitric oxide synthase (NOS2) expression in the lungs, which has been associated with severe influenza infections." (PMID 34691044, 2021). "The role of CCL2 in influenza infection has been investigated, but the findings are controversial." (PMID 28421067, 2017). "This is the first study evaluating the effects of CCL2 inhibitors for the treatment of influenza-induced disease and the results suggest that this class of drugs may not be suitable for treatment of severe influenza infections." (PMID 28435679, 2017). "CCL2, a macrophage chemo-attractant, is also heavily involved in influenza pathogenesis." (PMID 26393920, 2015). "The suite of cytokines and chemokines assessed here, namely, TNF-α, IL-6, CCL2, CCL3, CXCL2 and IL-1β, are known to promote the inflammation caused by influenza at early stages of the infection phase, i.e. during the cytokine storm, and have been shown to underpin the pathology and morbidity." (PMID 23577160, 2013). "In response to influenza viral entry, epithelial and immune cells induce pro-inflammatory cytokines and chemokines such as interleukin-1β, interleukin-6, tumor necrosis factor α (TNFα), CCL2, CCL3, and CCL5, which recruit macrophages and neutrophils to the site of infection to control the virus." (PMID 39846844, 2025). "In our study, we found increased expression of CCL2, CCL3, CXCL9, and CXCL10 in the heart following PR8, pH1N1, or H3N2 strains of influenza infection." (PMID 38750107, 2024). "We observed increased expression of Stat1, Stat2, Mx1, Oasl2, CCL2, CCL3, CXCL9, and CXCL10 in influenza-infected hearts and lungs when compared to PBS-treated controls." (PMID 38750107, 2024). "Empagliflozin treatment decreased the expression of the inflammatory cytokines IL-1β, IL-6, and CCL2; the percentage of inflammatory monocytes and inducible NO synthase–positive macrophages; and IFN response genes Stat1 and CXCL9 during influenza infection." (PMID 38112660, 2023). "We found that empagliflozin treatment decreased the expression of IL-6, CCL2, and CCL5 in BMDMs and IL-6 and CCL2 in RAW264.7 macrophages during influenza infection." (PMID 38112660, 2023). "During influenza, cytokines and chemokines such as type I and III interferons (IFNs), IL-6, CXCL8, CCL2, CCL3, CCL4, and CCL5 are produced at the site of infection (Wareing and others 2004)." (PMID 35674675, 2022). "Influenza infection leads to drastically elevated CCL2 concentration in the lungs of both young and aged mice, and anti‐IFNAR1 treatment repressed lung CCL2 concentrations in both young and aged mice." (PMID 34547174, 2021). "Expression of three cytokine indicators CCL2, CXCL10 and viral NA were selected to screen immunomodulators and antiviral agents for the treatment of influenza." (PMID 34955842, 2021). "It has been reported that people infected with influenza have higher levels of cytokines stimulated by type I IFNs (such as IL-6 and IFN-γ), and the chemokines IP-10 (also known as CXCL-10) and MCP-1 (CCL2)." (PMID 35154087, 2021). "Accordingly, our study has shown that rosiglitazone treatment decreased the levels of IL-6, IL-12, CCL-2 and CCL6 during influenza infection." (PMID 31159430, 2019). "Increased numbers of monocytes, cDCs, and PDCs in nasal wash of patients with influenza, higher than in patients with RSV.Increased levels of CCL2 (involved in recruitment of monocytes and DCs) in nasal wash of influenza patients." (PMID 28507549, 2017). "Taken together, our findings demonstrate that CCL2 is essential for H7N9 virus infection and thus that it is a potential therapeutic target for influenza." (PMID 28421067, 2017).
influenza (continued). "Pioglitazone treatment led to a reduction in the levels of CCL2 (MCP-1) and MCP-3 in the BAL fluid of influenza-infected mice." (PMID 25250029, 2014). "PBMCs in seasonal influenza patients were activated and expressed cytokines ex vivo (e.g. IL-6, CXCL8/IL-8, CCL2/MCP-1, CXCL10/IP-10, CXCL9/MIG); their ‘responsiveness’ to stimuli was shown to change dynamically during the illness course." (PMID 22022504, 2011). "Through such approach, it has been reported that different animals (such as primates, ferrets and mice) with influenza infection have been induced extraordinarily high expression of cytokines and chemokines (e.g. CXCL10, CCL2 and CXCL9)." (PMID 21819625, 2011). "Notably, CCL2 and CXCL10 levels are abnormally elevated in certain fatal cases of influenza infection." (PMID 40626651, 2025). "Prototypical cytokines and chemokines associated with influenza, including interferons (IFNs), tumor necrosis factor (TNF) α, interleukin (IL)−6, and CCL2 were upregulated throughout infection in the lungs but not the spleens of IAV-infected dams." (PMID 38190129, 2024). "The expression of interferon response genes STAT1, STAT2, Mx1, OASL2, ISG15, chemokines CCL2, CCL3, CXCL9 and CXCL10, and the frequency of neutrophils (CD45+CD11b+Ly6G+) and CD4+ T cells (CD45+CD4+) were all significantly increased in influenza-infected mice when compared to vehicle controls." (PMID 38750107, 2024). "Cytokines such as IL-4, IL-5, IL-6, IL-8, IL-13, and TNF-α, chemokines such as CCL2 and CCL3, and the MC proteases tryptase and chymase can be detected in the supernatants of influenza infected MC cultures and in the bronchioalveolar lavage fluid (BALF) of both influenza patients and infected mice." (PMID 33680987, 2021). "It was previously shown that CCL2 recruits CCR2+ inflammatory monocytes to the lung during severe influenza infection and prophylactic use of CCR2 antagonist reduces pulmonary immunopathology, markedly improving the survival of influenza infected mice." (PMID 32766256, 2020). "Other studies in mice lacking CXCR2 or CCR2, the primary receptor of CCL2, have shown that blockade of chemokine signaling reduces pulmonary recruitment and subsequently reduces injury and improves survival following influenza infection." (PMID 24223177, 2013). "CCL2/MCP-1 and CXCL8/IL-8 have been shown to recruit and activate monocytes/macrophages and neutrophils respectively in models of influenza pneumonia, leading to progression to ARDS." (PMID 22022504, 2011). "In an influenza model, direct comparison of the two sexes reveals that female mice exhibit greater morbidity and mortality than male mice, potentially because of elevated levels of cytokines, such as tumor necrosis factor (TNF)-α and C-C motif chemokine ligand 2 (CCL2), in female mice." (PMID 29284060, 2017). "Therefore, the increase in CCL-2, TNF-α and GM-CSF in our study may explain the observed increase in macrophages and neutrophils following CS and influenza infection." (PMID 26877172, 2016). "Similarly, CCL2 (Ccl2), a ligand for CCR2 that recruits CCR2+ inflammatory monocytes, as well as CXCL1 (Cxcl1), CXCL2 (Cxcl2), and CXCL5 (Cxcl5), which are ligands of CXCR2 that induce neutrophil infiltration in influenza-infected lungs, showed notable decreases in NOD.SCID mice." (PMID 37904257, 2023).
multiple sclerosis (98 papers, 2005 to 2026). A progressive autoimmune disorder affecting the central nervous system resulting in demyelination. "CCR2 and CCL2 have been consistently associated with a pathogenic role in BBB breakdown in patients with multiple sclerosis." (PMID 37056770, 2023). "CCL2 also drives pathogenic inflammation and has therefore been implicated in many autoinflammatory diseases, including multiple sclerosis." (PMID 34914635, 2022). "The expression of CCL2, aka MCP-1, has been associated with microglia activation in the pathogenesis of multiple sclerosis and AD." (PMID 29311768, 2017). "In multiple sclerosis, CC chemokines such as CCL2 and CCL5 promote central nervous system inflammation by regulating immune cell migration." (PMID 39104791, 2024). "The significance of CCL2 and CCR2 in MS is enigmatic because CCL2 levels are consistently decreased in the cerebrospinal fluid of pwMS despite abundant expression within lesioned multiple sclerosis tissues." (PMID 37893243, 2023). "During experimental autoimmune encephalomyelitis (EAE), an IL-17–driven model of multiple sclerosis, CCL2 produced by lymph node (LN) stromal cells was essential for immunopathology." (PMID 34914635, 2022). "Recently, astrocytic activation of cPLA2 bound directly with MAVS enhanced NF-ĸB pathways to produce proinflammatory factors such as Ccl2 and Nos2 in an animal model of multiple sclerosis (MS)." (PMID 35705959, 2022). "In experimental multiple sclerosis mouse model, gal3−/− mice infected with Theiler’s murine encephalomyelitis virus have reduced CCL2, CCL5, CCL8, and CXCL10 expression and lower number of infiltrating cells in the brain subventricular zone." (PMID 28217127, 2017). "It is noteworthy that in specimens from patients with multiple sclerosis, astrocytes surrounding demyelinating lesions express Ccl-2." (PMID 27596241, 2016). "For instance, astroglial chemokines have an influence upon microglia/macrophage activation in multiple sclerosis with CCL2 (MCP-1) and CXCL10 (IP-10) directing reactive gliosis." (PMID 25977914, 2015). "The chemokine MCP-1 or CCL2, which plays a role in both neuroinflammation and multiple sclerosis, is released by murine, rat and human microglia in vitro." (PMID 24675728, 2014). "The chemokine CCL2 is a critical mediator of neuroinflammation in diseases such as multiple sclerosis (MS) and its animal model, experimental autoimmune encephalomyelitis (EAE)." (PMID 24589378, 2014). "Activated Mφs have been described releasing CCL2 in neuro-inflammatory conditions such as multiple sclerosis in vivo." (PMID 24142887, 2013). "From these chemokines, Ccl2 plays a critical role in multiple sclerosis and in its murine model, experimental autoimmune encephalomyelitis (EAE)." (PMID 23637839, 2013). "CCL2 expression level is also related to another neurodegenerative disorder, multiple sclerosis (MS); CCL2 level is downregulated in cerebrospinal fluid from MS patients." (PMID 22666624, 2012). "This is consistent with a previous report showing that hCMEC/D3 cells express lower levels of MCP-1/CCL2 than two primary human brain endothelial cells generated from multiple sclerosis brain tissue or from temporal lobe resections from epileptic patients." (PMID 22768975, 2012). "Our recent genetic scans in families identified haplotypes in the genes of CCL2, CCL3 and CCL11-CCL8-CCL13 which showed association with multiple sclerosis." (PMID 15730561, 2005). "Additionally, increased levels of CXCL10 correlated with markers of intrathecal inflammation were found in CSF of patients with multiple sclerosis (MS), while CCL2 was suppressed." (PMID 38931342, 2024). "However, CCL2 also triggers axonal damage in mouse models of motoneuron disease and multiple sclerosis." (PMID 27581653, 2016).
multiple sclerosis (continued). "CC Chemokine 2 (CCL2) namely Monocyte chemotactic protein-1 (MCP-1) and highly expressed in the cerebrospinal fluid of human multiple sclerosis (MS) patients, and plays a key role in regulating in the migration of monocytes to the CNS." (PMID 35281298, 2022). "In patients with multiple sclerosis, the concentration of CXCL10 and CCL2 in CSF correlates with disease activity, returning to normal levels upon therapy." (PMID 34764955, 2021). "The loci identified included SNPs in immune response genes linked to autoimmune diseases including Crohn’s disease, ulcerative colitis, multiple sclerosis, and T1D (CD5, CCL2, IL23R, CD86, HLA, C11ORF30-LRRC32, CLEC16A)." (PMID 29454391, 2018). "Complementing the genetic associations, we also detected a distinct regional expression regulation for CCL2, CCL7 and CCL8 in correlation with chronic inflammation in multiple sclerosis brains." (PMID 15730561, 2005). "We stained for GFAP+ astrocytes, CCL2-producing (RFP+) cells, and Iba-1+ cells, which include microglia, macrophages, and mature monocytes, as these cells have been found to produce CCL2 in other neuroinflammatory diseases, including multiple sclerosis." (PMID 38206985, 2024). "HIV infection in leukocytes has been shown to enhance their transmigration across the blood–brain barrier (BBB), a process facilitated by soluble inflammatory factors, including Chemokine (C-C motif) Ligand 2 (CCL2), which is also a key mediator in the pathogenesis of multiple sclerosis." (PMID 39408789, 2024). "In fact, the levels of the chemokines CXCL1 (growth related oncogene, GRO) and CCL2 (monocyte chemoattractant protein-1, MCP-1) varied in their expression along the demyelination process in taiep rats and contribute to the deficit of myelination by OPC, similar to multiple sclerosis (MS) patients." (PMID 32817660, 2020). "Finally, MCP1 (CCL2) is a chemoattractant for monocytes and basophils and has an important role in several inflammatory diseases, such as multiple sclerosis and inflammatory bowel disease." (PMID 27447618, 2016). "Elevated CNS expression of CCL2 has been a consistent observation among the different paradigms of experimental autoimmune encephalomyelitis (EAE), a CNS demyelinating inflammatory disease that serves as a model for multiple sclerosis." (PMID 24444311, 2014). "Astrocytes are a major CNS source of CCL2 in both EAE and multiple sclerosis (MS)." (PMID 24444311, 2014). "Previous studies in biopsies of patients with multiple sclerosis and after brain injury in mice have suggested that CCL2 is expressed by astrocytes but no co-localization analysis of the proteins was conducted." (PMID 22319587, 2012).
psoriasis (98 papers, 2007 to 2026). An autoimmune condition characterized by red, well-delineated plaques with silvery scales that are usually on the extensor surfaces and scalp. "For example, c-Jun is a key positive regulator of CCL2 and IL-23 expression in DC and is therefore closely associated with chronic autoimmune diseases, such as psoriasis." (PMID 37445800, 2023). "Accordingly, genes associated with psoriasis, including S100a8, S100a9, Camp, Tnf, Il1b, Il23a, and Ccl2, were strongly downregulated." (PMID 35869084, 2022). "The inflammatory factors IL6 and CCL2 (encoding MCP1 protein) were highly overexpressed as a result of the combined psoriasis-induction stimuli that reflects acute inflammation changes." (PMID 33986690, 2021). "Molecular analysis of the skin of IgG- and anti-IL36R-treated K14-IL17Aind mice revealed effective suppression of psoriasis-associated cytokines (Il36a, Il36g, Il36b, Il23a, and Tnf), chemokines (Cxcl1, Cxcl5, and Ccl2) and antimicrobial-peptides (such as Defb4) on mRNA level." (PMID 38162658, 2023). "Additionally, CCL2, a neutrophil chemokine implicated in angiogenesis and the pathological changes of psoriatic lesions, was markedly elevated in psoriasis-induced mice." (PMID 38007430, 2023). "Chemokines encoded by CCR7, CCL2, CCL19, CXCL8, CXCL1, and CXCL2 genes have been identified as potential biomarkers of psoriasis." (PMID 40906403, 2025). "CCL2 primarily recruits monocytes and macrophages and is consistently elevated in multiple inflammatory skin diseases including psoriasis and atopic dermatitis." (PMID 41264606, 2025). "Monocyte chemotactic protein 1 (MCP-1/CCL2) has also recently been proposed as a possible biomarker to track the development of psoriasis." (PMID 38399427, 2024). "Although carlumab and bindarit, inhibitors focusing on CCL2, have been considered for systemic sclerosis, their effectiveness in psoriasis has yet to be assessed." (PMID 38829444, 2024). "Numerous studies have documented increased CCL2 expression in both the skin lesions and peripheral blood of individuals with psoriasis and other skin conditions." (PMID 38829444, 2024). "In fact, a notable trend of increased CCL2 expression was observed in both AD and psoriasis lesions." (PMID 38035099, 2023). "Elevated levels of circulatory CCL2 in patients with psoriasis have been observed in several studies." (PMID 37744329, 2023). "IFN-γ is a notable cytokine in psoriatic lesions that can induce the upregulation of Th1 and dendritic cells chemokines, such as CXCL10 and CCL2, which are expressed prominently in psoriasis." (PMID 33149756, 2020). "These include proinflammatory chemokines common to AD and psoriasis, namely CCL2, CCL5 and CCL7, that mediate recruitment of monocytes, T cells, and eosinophils." (PMID 28530223, 2017). "Similar to CCL2, CXCL9 has been reported to participate in monocyte proliferation associated disease, including psoriasis." (PMID 28787010, 2017). "Transfection of ECs with psoriasis-associated CARD14 mutations resulted in increased expression of several chemokines, including IL-8, CCL2, and CXCL10." (PMID 25369198, 2014). "Transfection of dermal ECs with psoriasis-associated CARD14 mutations resulted in increased expression of several chemokines, including CXCL10, IL-8, and CCL2." (PMID 25369198, 2014). "Furthermore, the transcriptional signature from affected skin revealed upregulation of key human psoriasis genes, including Lcn2 and Defb4, cytokines Tnf, Il1b, and Il36a/g, and chemokine ligands Ccl2, Cxcl9, and Ccl20." (PMID 38528069, 2024). "To further verify whether SFN could modulate the expression of inflammatory factors and chemokines during psoriasis development, we evaluated the mRNA levels of Il1b, Il6, and Ccl2 using qRT‒PCR." (PMID 38007430, 2023).